ORMDL3 (ORMDL sphingolipid biosynthesis regulator 3)
Diseases named in the same sentence as ORMDL3 in open-access papers (continued):
Sharing a sentence is not in itself a finding about the gene and the disease.
childhood asthma (28 papers, 2009 to 2026). "Their importance in humans is exemplified by a major childhood asthma susceptibility locus that upregulates ORMDL3 expression." (PMID 38347162, 2024). "Previous studies have reported that the 17q21 locus alleles in genes GSDMA, GSDMB, IKZF3, ZPBP2, and ORMDL3 are associated with increased risk and severity of childhood asthma and increased number of early wheezing illnesses." (PMID 36967681, 2023). "Oroscomucoid 3 (ORMDL3) has been linked to susceptibility of childhood asthma and respiratory viral infection." (PMID 34001091, 2021). "Genome-wide association studies have provided evidence that altered ORMDL3 expression is linked to risk for inflammatory disorders, including childhood asthma and ulcerative colitis." (PMID 30683667, 2019). "The TT-genotype of ADAM33 rs511898 (p = 0.03), the CG/GG-genotype of ADAM33 rs528557 (p = 0.08) and the TT-genotype of ORMDL3/GSDMB rs7216389 (p = 0.08) were negatively associated with childhood asthma." (PMID 25768087, 2015). "The TAGC-only colocalization was an meQTL-GWAS pair that was associated with cg10374813 and the three TAGC and childhood onset asthma colocalizations were eQTL-meQTL-GWAS triplets associated with two genes (ORMDL3 and ERBB2) and two CpGs (cg18711369 and cg2270401)." (PMID 34629083, 2021). "Moreover, ORMDL3 has also been extensively reported to be linked with other inflammatory diseases, including childhood asthma, inflammatory bowel diseases, rheumatoid arthritis, and Crohn’s disease." (PMID 34872583, 2021). "Although the transcript level of ORMDL3 is strongly correlated to susceptibility to childhood asthma, its role remains unclear." (PMID 22481967, 2012). "As both childhood asthma and allergic rhinitis are associated with increased Th2 responses, one would have expected that ORMDL3 enhancing Th2 responses would result in association of ORMDL3 with both childhood asthma and allergic rhinitis, which is not the case." (PMID 33661765, 2021). "ORMDL3, a widely studied gene in pediatric asthma that plays a role in sphingolipid biosynthesis, was identified as one of these transcriptomic modules." (PMID 37762787, 2023). "Susceptibility to PD and childhood asthma have been linked to genetic variants of GBA1 and ORMDL3, respectively, tying these disorders directly to the SL metabolic pathway." (PMID 30683667, 2019). "Genome-wide association studies link ORM-Like protein isoform 3 (ORMDL3) a member of the ORM gene family, to the onset of childhood asthma." (PMID 26431038, 2015). "Our GWAS dataset supported an association between identical SNPs reported in ORMDL3/GSDMB/GSDMA, IL5/RAD50/IL13, HLA-DR/DQ, and SMAD3 and pediatric asthma (P<0.05)." (PMID 21814517, 2011). "In the ADEM study, the minor alleles of ADAM33 rs511898 and rs528557 and the ORMDL3/GSDMB rs7216389 polymorphisms were negatively associated, whereas the minor alleles of IL4 rs2243250 and rs2070874 polymorphisms were positively associated with childhood asthma." (PMID 25768087, 2015). "In this latest study, genes such as ORMDL3 and GSDMB expectedly showed the strongest significance to childhood asthma (random-effect P values of 5.24 × 10-21 and 6.45 × 10-23 respectively)." (PMID 22188591, 2011). "In a genome-wide association study, it was reported that 17q21 loci which include ORMDL3/GSDMB genes is highly correlated with childhood asthma, but unlike our results, GSDMB is not correlated to total IgE serum levels." (PMID 36201519, 2022).
Crohn disease (14 papers, 2009 to 2024). A gastrointestinal disorder characterized by chronic inflammation involving all layers of the intestinal wall, noncaseating granulomas affecting the intestinal wall and regional lymph nodes, and transmural fibrosis. "Although clinical association studies correlated an increased expression of ORMDL3 with risk of Crohn’s disease, gut biopsy samples from Crohn’s disease patients showed comparable levels of ORMDL3 expression with controls." (PMID 38715613, 2024). "Several other genes such as ORMDL3 and IL-10 have also been associated with both T1D and Crohn's disease." (PMID 26734582, 2015).
autoimmune disease (11 papers, 2016 to 2026). A disorder resulting from loss of function or tissue destruction of an organ or multiple organs, arising from humoral or cellular immune responses of the individual to their own tissue constituents. "Suppressed expression of ORMDL3 has been associated with the increased occurrence of autoimmune diseases." (PMID 38715613, 2024). "Recent studies show that ORMDL3's function extends beyond the respiratory system, with involvement in obesity, diabetes, atherosclerosis, inflammatory bowel disease, autoimmune diseases, and various cancers." (PMID 41884618, 2026). "Compared with ORMDL3− cholangiocytes, there were 77 significantly differentially expressed genes among ORMDL3+ cholangiocytes (FDR < 0.05), and these significant genes were associated with autoimmune diseases-related functional terms or pathways." (PMID 34872583, 2021). "IRF8, TMEM39A and IKZF3-ZPBP2 were previously identified as susceptibility loci for SLE in the multiracial replication study, Besides, ORMDL3 and GSDMB were found to have susceptibility loci for autoimmune diseases." (PMID 28427360, 2017). "Additionally, several studies found genetic variants in orosomucoid like 3 (ORMDL3) and gasdermin B (GSDMB) were associated with the risk of autoimmune disease." (PMID 28427360, 2017).
inflammatory bowel disease (11 papers, 2013 to 2026). A spectrum of small and large bowel inflammatory diseases of unknown etiology. "Genome-wide association studies in inflammatory bowel disease have identified risk loci in the orosomucoid-like protein 3/ORMDL sphingolipid biosynthesis regulator 3 (ORMDL3) gene to confer susceptibility to ulcerative colitis (UC), but the underlying functional relevance remains unexplored." (PMID 38417794, 2024). "Indeed, anomalous autophagy has been linked to inflammatory bowel diseases, a spectrum of inflammatory disorders to which ORMDL3 has been genetically associated." (PMID 30897694, 2019). "Large GWAS studies have identified a significant association between ORMDL3 expression and inflammatory bowel diseases (IBD) including Crohn’s and ulcerative colitis." (PMID 33424845, 2020). "SNP variants have also linked ORMDL3 to inflammatory bowel disease (IBD) and Type I diabetes, suggesting that ORMDL3 may be involved in dysregulation of the immune system." (PMID 23369242, 2013).
Obesity (8 papers, 2017 to 2026). Accumulation of substantial excess body fat. "ORMDL3 gene polymorphism has been associated with type 1 diabetes and was suggested to be an obesity-related gene, whereby its expression negatively correlated with body mass index BMI." (PMID 38081412, 2024). "Our findings revealed that β-cell loss of Ormdl3 during obesity leads to increased generation of islet very long chain ceramide species, hinting at a potential regulatory axis in which ORMDL3 contributes to control of this sphingolipid class." (PMID 37124760, 2023). "ORMDL3 is one of three isoforms of this protein family, and genome-wide association studies (GWAS) have identified Ormdl3 as an obesity-related gene whose expression negatively correlates with body mass index." (PMID 37124760, 2023). "Genome-wide association studies identified the SPT suppressor ORMDL3 as an obesity-related gene, and its expression in human subcutaneous WAT was inversely correlated with BMI." (PMID 36671552, 2023). "Another intriguing factor that has emerged in the context of obesity-induced epithelial airway remodeling is ORM1-Like Protein 3 (ORMDL3) and 17q21-related genes." (PMID 38562155, 2024). "ORMDL3, a negative regulator of the rate-limiting step in ceramide biosynthesis, has been identified as an obesity-related gene." (PMID 38081412, 2024). "Recently, attention has been focused on ORMDL sphingolipid biosynthesis regulator 3 (ORMDL3), which has been identified as an obesity-related gene that negatively correlates with the body mass index." (PMID 38081412, 2024). "Together, these results suggest a potential role for ORMDL3 expression in inter-organ cross-talk that can maintains overall metabolic homeostasis in obesity and NASH development." (PMID 38081412, 2024). "Although Ormdl3 was reported to be upregulated in the β-cells of ob/ob mice that spontaneously develop obesity, another study showed that loss of Ormdl3 in β-cells did not alter glucose tolerance or insulin sensitivity." (PMID 38081412, 2024). "While this suggests that ORMDL3 plays a role in obesity, the role of ORMDL3 in β-cell physiology and pathology remains unknown." (PMID 37124760, 2023). "Therefore, we assessed the role of ORMDL3 in diet-induced obesity and development of NASH." (PMID 38081412, 2024). "Therefore, we sought to assess the role of ORMDL3 in obesity." (PMID 38081412, 2024). "Taken together, our results suggest that while loss of β-cell Ormdl3 alone does not impinge upon systemic metabolism or β-cell function in nutritionally unstressed conditions, deletion of Ormdl3 results in a significant increase in very long chain ceramide species in obesity." (PMID 37124760, 2023). "Further molecular studies at the protein level are, however, required to determine the function of ORMDL3 and LACTB in connection with obesity." (PMID 29666371, 2018). "Obesity-induced epithelial remodeling may involve various factors, including HMGB1, the role of leptin, CysLTs, ORMDL3, matrikines like PGP, and cytokines such as IL-4 and IFN-γ, which may contribute to epithelial alterations." (PMID 38562155, 2024). "Importantly, ORMDL3 is downregulated in the WAT of obese mice and humans, and its deletion resembles the metabolic phenotypes of obesity induced by a high-fat diet (HFD)." (PMID 36671552, 2023). "Other hub genes, including CCDC50, ORMDL3, PCCA and NAALAD2, have diverse cellular functions and have not been previously implicated as obesity candidate genes." (PMID 28496128, 2017).
diabetes (7 papers, 2019 to 2026). "In this study, we examined intestinal changes in a Sprague Dawley rat model of experimentally induced diabetes, focusing on ORMDL3 expression and its relationship with endoplasmic reticulum (ER) stress and autophagy." (PMID 41182648, 2025). "ORMDL3 levels in islets from NOD mice showed a mild increase before diabetes onset, but a gradual decrease subsequently." (PMID 31061237, 2019). "Although genome-wide association studies (GWAS) have implicated the orosomucoid-like protein 3 (ORMDL3), also known as ORMDL sphingolipid biosynthesis regulator 3, in susceptibility to both IBD and DM, its precise role in diabetes-associated intestinal alterations remains poorly defined." (PMID 41182648, 2025). "Together, our data suggest that ORMDL3 may increase beta cell proliferation through ATF6 as a beta-cell compensation against diabetes." (PMID 31061237, 2019). "Next, we aimed to examine the changes in ORMDL3 in beta cells at diabetes onset." (PMID 31061237, 2019). "Together, our data suggest that ORMDL3 may increase beta cell proliferation through ATF6 as an early compensatory change in response to diabetes." (PMID 31061237, 2019). "We are interested in assessing the role of ORMDL3 before diabetes onset, since it may provide some novel mechanisms to resist the development of diabetes." (PMID 31061237, 2019). "ORMDL3 levels in islets from NOD mice, a mouse model for T1D in humans, showed a mild increase before diabetes onset, but a gradual decrease subsequently." (PMID 31061237, 2019).
type 1 diabetes (7 papers, 2012 to 2024). "Next, we discovered eight gene polymorphisms (ORMDL3, SPHK2, B4GALNT1, SLC1A5, GALC, PPARD, PPARG and B4GALT1) involved in sphingolipid metabolism that contribute to the genetic predisposition to type 1 diabetes." (PMID 29671030, 2018). "For six genes (ORMDL3, GALC, SPHK2, SLC1A5, PPARD and B4GALT1) the SNPs with the strongest association with type 1 diabetes (lowest p value) also acted as cis-eQTLs, suggesting that these SNPs regulate the expression of their associated genes." (PMID 29671030, 2018).
Allergy (6 papers, 2013 to 2022). An allergy is an immune response or reaction to substances that are usually not harmful. "Class switching to the allergy-associated IgE was unaffected by the loss of ORMDL3, although there was a modest decrease in the levels of Alternaria-specific IgE (0.78OD vs 0.61OD) in Ormdl3 KO miceMer." (PMID 27623174, 2017). "This decreased activity of S1PL is reversed by silencing ORMDL3 or adding an antioxidant, thereby suggesting that the AhR-ligand axis regulates the time-dependent upregulation of ORMDL3/S1PL complex, particularly in allergic diseases." (PMID 36601108, 2022). "ORMDL3 inhibits the rate-limiting enzyme serine palmitoyl CoA transferase in the de novo sphingolipid synthesis, which results in decreased sphingolipid synthesis and increased airway hyperreactivity, independent of allergy or inflammation in mouse models." (PMID 33339279, 2020).
allergic asthma (5 papers, 2013 to 2025). A asthma with a basis in a pathological type I hypersensitivity reaction. "A decade ago, several genome wide association studies revealed single nucleotide polymorphisms associated with increased ORMDL3 protein expression and susceptibility to allergic asthma." (PMID 33424845, 2020). "In a sample of pediatric asthmatics, sphingolipids were reduced in those with high-risk variants in the 17q21 locus that promotes expression of ORMDL3 and in those with non-allergic asthma in comparison to those with allergic asthma or healthy controls." (PMID 32155960, 2020). "This novel study was the first to posit the intriguing theory that ORMDL3 overexpression might skew CD4+ T cell differentiation toward a Th2 imbalance, contributing and priming the immune response toward allergic asthma." (PMID 33424845, 2020). "MUC5B, ORMDL3, MUC5AC, CHI3L1, CLCA1, and IL-33 display a distinctly high non-specific relationship with allergic and non-allergic asthma." (PMID 33936056, 2021).
Autoimmunity (5 papers, 2016 to 2023). The occurrence of an immune reaction against the organism's own cells or tissues. "ORMDL3 is also implicated as a causal gene of rheumatoid arthritis, an autoimmune disorder characterized by chronic inflammation of the joints." (PMID 33424845, 2020). "ORMDL3-mediated ER stress and UPR may exacerbate proinflammatory cytokine production and tissue inflammation associated with these autoimmune disorders." (PMID 33424845, 2020). "Furthermore, we found that heterozygous and homozygous carriers of the risk alleles rs12150079 (ORMDL3) and rs33988101 (SPHK2) had lower levels of T cell autoimmunity (p = 0.042 and p = 0.017, respectively)." (PMID 29671030, 2018). "Using this model, they successfully showed that risk variants of autoimmunity were enriched in cell-state-dependent eQTLs (e.g., ORMDL3 and CTLA4 loci), indicating that cell-state context is crucial to understanding the genetic etiology of autoimmunity." (PMID 36980846, 2023).
primary biliary cirrhosis (5 papers, 2012 to 2021). "Here, we show an efficient approach for identification of a functional variant in a primary biliary cholangitis (PBC)-susceptible region, chromosome 17q12-21 (ORMDL3-GSDMB-ZPBP2-IKZF3)." (PMID 28588209, 2017).
atherosclerosis (4 papers, 2015 to 2026). A disease characterized by the build-up of fatty material and calcium deposition in the arterial wall resulting in partial or complete occlusion of the arterial lumen. "One study suggests that ORMDL3 increases the risk of atherosclerosis in the Chinese Han population." (PMID 39920588, 2025). "In this study, shRNA-mediated silencing of ORMDL3 alleviated ox-LDL, basal, and serum starvation-induced endothelial cell autophagy to a certain extent, suggesting that ORMDL3 may be a causative gene associated with endothelial cell autophagy in the pathogenesis of atherosclerosis." (PMID 39920588, 2025). "Moreover, ORMDL sphingolipid biosynthesis regulator 3 (ORMDL3), as an essential regulator of lipid metabolism, inflammation and ER stress, is involved in the pathogenesis of atherosclerosis." (PMID 29774216, 2018). "Therefore, ORMDL3 mediates ox-LDL-induced autophagy in endothelial cells in atherosclerosis." (PMID 29774216, 2018).
breast carcinoma (4 papers, 2016 to 2020). "We found one gene, ORMDL3, whose low and high modes were both associated with worse survival and higher tumor grade in breast cancer patients in multiple patient cohorts." (PMID 30621577, 2019). "Applying our EM algorithm to the Metabric breast cancer dataset, we identified the gene ORMDL3, whose low and high expression are both associated with higher tumor grade and worse survival outcome." (PMID 30621577, 2019). "Variants of ORMDL3 (ORMDL Sphingolipid Biosynthesis Regulator 3) were expressed in different breast cancer cell lines." (PMID 30404658, 2018). "Our analysis of breast cancer datasets suggest that the gene ORMDL3 may have an unexploited tumor suppressive function." (PMID 30621577, 2019). "We noticed that ORMDL3 is only about 200 kb away from ERBB2/HER2, which is a well-known tumor driver in multiple cancers, including breast cancer." (PMID 30621577, 2019). "Although the functional relevance of ORMDL3 to breast cancer has not been reported, it has been shown to be differentially expressed in ER+ tumors." (PMID 30404658, 2018).
systemic lupus erythematosus (4 papers, 2010 to 2024). An autoimmune multi-organ disease typically associated with vasculopathy and autoantibody production. "This study aimed to assess the association between 14 single nucleotide polymorphisms (SNPs) in six genes (IRF8, TMEM39A, IKZF3, ORMDL3, GSDMB, and ZPBP2) and systemic lupus erythematosus (SLE) in a Chinese Han population sample." (PMID 28427360, 2017).
colitis (3 papers, 2017 to 2024). Inflammation of the colon. "ORMDL3 knockdown in DSS-induced colitis mice model showed significant reversal of the disease pathology." (PMID 38417794, 2024). "Accordingly, knockdown of ORMDL3 in a dextran sodium sulfate -induced colitis mouse model showed reduced colitis severity." (PMID 38417794, 2024). "To understand the role of ORMDL3 during DSS-induced colitis, we downregulated ORMDL3 expression in the animal using lentivirus containing ORMDL3 shRNA injected via intraperitoneal route in mice." (PMID 38417794, 2024). "Further, we found that the reduction of ORMDL3 expression level in the mice model of colitis reduces inflammation as well as disease severity." (PMID 38417794, 2024). "In order to access the role of ORMDL3 in the colitis formation, we organized the animal into three experimental groups namely, control, DSS treatment with nontargeted shRNA (DSS-sh-NT), and DSS treatment with ORMDL3 shRNA (DSS-sh-ORMDL3)." (PMID 38417794, 2024). "Importantly, TNF-α level in mice after ORMDL3 knockdown was similar to the DSS-sh-NT mice suggesting that ORMDL3 expression level did not affect TNF-α level during DSS-induced colitis." (PMID 38417794, 2024).
airway hyperresponsiveness (2 papers, 2021 to 2022). "The complexity of ORMDL3 function in vivo was underlined by the study showing that selective deletion of ORMDL3 in the airway epithelium challenged with allergen unexpectedly exhibit increased airway hyperresponsiveness." (PMID 34560079, 2021).
atopic asthma (2 papers, 2021 to 2025). An asthma that is characterized by symptoms that are triggered by an allergic reaction caused by inhaled allergens such as dust mite allergen, pet dander, pollen and mold. "Treatment with ICSs has been shown to enhance the expression level of the ORMDL3 gene in children with atopic asthma." (PMID 40573242, 2025).
breast tumor (2 papers, 2017 to 2019). "KANSL1 has also been reported fused with ORMDL3 and LAYN in one breast tumor and with UNC45B in one lung tumor." (PMID 28423358, 2017).